WDR76 (WD repeat domain 76)
Diseases named in the same sentence as WDR76 in open-access papers (continued):
Sharing a sentence is not in itself a finding about the gene and the disease.
tumor (continued). "Finally, WDR76 was shown to be involved in LGG tumor immunity by promoting the infiltration of immune cells, such as M2 macrophages, and the expression of immune checkpoints, such as PDCD1 (encoding PD-1)." (PMID 38173030, 2024). "Taken together, this study revealed an irreplaceable role of WDR76 in regulating tumor immunity in LGG, which may lead to new opportunities for immunotherapy in patients." (PMID 38173030, 2024). "With the popularity of immunotherapies in the LGG landscape, the role of WDR76 in tumor immune mechanisms may be a breakthrough to further improve patient outcomes." (PMID 38173030, 2024). "Moreover, since different subtypes of immune cells perform distinct functions in the tumor microenvironment, we further explored the relationship between WDR76 expression and the infiltration of specific tumor cell subtypes using the ESTIMATE analysis." (PMID 38173030, 2024). "Our study demonstrates that WDR76 functions as a tumor suppressor via RAS degradation." (PMID 30655611, 2019). "Indeed, WDR76 deficiency enhanced the formation of malignant liver tumors and lung metastasis providing strong evidence that WDR76 is a potential tumor suppressor." (PMID 30655611, 2019). "However, the function of WDR76 in human tumor tissue still needs further research." (PMID 37081180, 2023). "We examined the phenotypes of Wdr76-knockout (Wdr76−/−) mice and found that loss of Wdr76 did not induce tumor formation in 15-week-old mice; however, it induced significant crypt lengthening and hyper-proliferation, which are characteristics of mice that harbor oncogenic K-Ras mutations." (PMID 31362761, 2019). "The present study is the first to reveal the definitive role of WDR76 in LGG carcinogenesis and tumor immunity." (PMID 38173030, 2024). "This study aimed to report the prognostic value of WDR76 in LGG and its involvement in tumor immunity." (PMID 38173030, 2024). "Transcriptomic data from public databases were multifariously analyzed to explore the role of WDR76 in LGG pathology and tumor immunity." (PMID 38173030, 2024). "WDR76 has been shown to destabilize RAS and serves as a tumor inhibitor in CRC by suppressing cancer stem cell activation." (PMID 36681855, 2023). "They successfully identified WDR76, a CUL4-DDB1 ubiquitin E3 ligase interacting protein, as a tumor suppressor candidate." (PMID 33714259, 2021). "The importance of KRAS stability in CSC activation was also demonstrated by work on WD repeat protein 76 (WDR76), an E3 ligase that destabilises RAS, thereby acting as a tumour suppressor." (PMID 33802849, 2021). "The inverse correlation between WDR76 expression and LGR5 expression in murine and human CRCs emphasizes the pathological importance of WDR76 destabilizing RAS as a tumor suppressor inhibiting CSC activities." (PMID 31362761, 2019). "Tissue section staining also showed markedly higher intensities of RAS staining in HCC tissues compared with normal tissue, and negative correlation with the staining intensities of WDR76 in tumor tissues." (PMID 33714259, 2021). "Researchers hypothesized that WDR76 destabilized RAS through Wnt/β-catenin signaling pathway and further acted as a tumor suppressor to inhibit CSC activation in CRC." (PMID 33714259, 2021). "In order to verify the differential expression, we further compared WDR76 expression between LUAD and normal tissues in data sets GSE140797 (7 pairs tumor and normal tissues), GSE27262 (25 pairs tumor and normal tissues) and GSE18842 (44 pairs tumor and normal tissues) from GEO database." (PMID 34707943, 2021). "The pathological significance of the aberrancy in the RAS stability regulation via WDR76 was supported by the inverse correlation between expression levels of RAS and WDR76 in non-tumor and tumor tissues of HCC patients." (PMID 30655611, 2019). "We investigated whether WDR76 destabilizes RAS and acts as a tumor suppressor inhibiting CSC activation in CRC." (PMID 31362761, 2019).
tumor (continued). "Moreover, the RAS staining intensities are much higher in tumor tissues compared with those in paired non-tumor tissues and inversely correlate with the WDR76 staining intensities in human HCC tissues." (PMID 30655611, 2019). "Comparison of the protein expression ratios (tumor/non-tumor) of RAS and WDR76 from the regions of the tumor and paired non-tumor tissues further revealed a significant negative correlation between RAS and WDR76 (non-tumor; r = −0.6671, p < 0.001 and tumor; r = −0.4573, p = 0.002)." (PMID 30655611, 2019).
cancer (9 papers, 2019 to 2024). A tumor composed of atypical neoplastic, often pleomorphic cells that invade other tissues. "WDR76 deficient mice were reported to develop more tumors with bigger sizes than control mice and their tumors showed increased proliferation and cancer stem cell activation." (PMID 33282547, 2020). "With the increase in cancer-related research, the function of WDR76, which contains a WDR domain at the protein C-terminus has been demonstrated." (PMID 38173030, 2024). "Similar results have also confirmed that WDR76 causes instability of the RAS in CRC, impairing the proliferation and activation of cancer stem cells by inhibiting the Wnt/β-catenin signaling pathway." (PMID 38173030, 2024). "Despite the possible involvement of WDR76 in multiple biological processes, its exact role in cancers remains to be elucidated." (PMID 34707943, 2021). "Molecular action of WDR76 in suppressing LSH incorporation into a functional complex corresponded to the distinct ferroptosis in cancer cells." (PMID 33714259, 2021). "WDR76 caused the ubiquitination-dependent proteasomal degradation of both wild-type and oncogenic K-RAS and had suppressive effects on cancer stemness in CRC cell line-derived spheroids harboring both APC and K-RAS mutations." (PMID 31362761, 2019). "Moreover, WDR76 can be a novel independent risk factor for LGG, and it can also lead to the malignant progression of LGG through its involvement in multiple cancer pathways." (PMID 38173030, 2024). "The effects of overexpression and knockdown of WDR76 on decrement and increment of RAS protein levels, respectively, were verified in cancer cells including RAS-mutated cancer cells, indicating that WDR76 degrades RAS proteins regardless of their mutational status." (PMID 30655611, 2019). "We next tested whether WDR76 degraded oncogenic RAS mutants that frequently occur in cancer cells." (PMID 30655611, 2019). "Our studies present important evidence for a mechanism that controls RAS activity via regulation of its protein stability involving tumorigenesis and suggest that a mechanism regulating RAS stability via WDR76 may lead to development of strategies against human cancer." (PMID 30655611, 2019). "WD repeat domain 76 (WDR76) is a predicted member of the WD40-repeat-containing domain superfamily, whose function is poorly characterized in cancers (Yang, Wang & Chen, 2021)." (PMID 34707943, 2021). "WD repeat domain 76 (WDR76) is a predicted member of the WD40-repeat-containing domain superfamily and possibly involves in various biological processes, but its function in cancers is poorly characterized." (PMID 34707943, 2021). "A natural product, Kurarinone, which was reported to have anti-cancer activity against various cancers, was identified to decrease the protein level of KRAS by proteasomal degradation dependent on an E3 ubiquitin ligase WDR76." (PMID 37110848, 2023).
metabolic disorders (1 paper, 2019). "To identify the effects of WDR76 deficiency on metabolic disorders, we measured triglyceride (TG), total cholesterol (TC), and free fatty acid (FFA) levels in the serum of the HFD-fed Wdr76+/+ and Wdr76−/− mice." (PMID 31873167, 2019).
WDR76 also shares sentences with these, for which no sentence is quoted: anaplastic oligodendroglioma (1 paper); bladder cancer (1); leukemia (1); melanoma (1).